PEG10 (paternally expressed 10)
Description:
Retrotransposon-derived protein that binds its own mRNA and self-assembles into virion-like capsids. Forms virion-like extracellular vesicles that encapsulate their own mRNA and are released from cells, enabling intercellular transfer of PEG10 mRNA. Binds its own mRNA in the 5'-UTR region, in the region near the boundary between the nucleocapsid (NC) and protease (PRO) coding sequences and in the beginning of the 3'-UTR region. Involved in placenta formation: required for trophoblast stem cells differentiation (By similarity). Involved at the immediate early stage of adipocyte differentiation (By similarity). Overexpressed in many cancers and enhances tumor progression: promotes cell proliferation by driving cell cycle progression from G0/G1. Enhances cancer progression by inhibiting the TGF-beta signaling, possibly via interaction with the TGF-beta receptor ACVRL1. May bind to the 5'-GCCTGTCTTT-3' DNA sequence of the MB1 domain in the myelin basic protein (MBP) promoter; additional evidences are however required to confirm this result (By similarity).
Synonyms: EDR; MAR2; MART2; RGAG3; KIAA1051; HB-1; MEF3L; SIRH1; RTL2
Tractability: Antibody: UniProt places it where antibodies can reach, with high confidence; its Gene Ontology location is reachable by antibodies, with medium confidence. PROTAC: UniProt records ubiquitination sites on it; ubiquitination databases record sites on it; its protein half-life has been measured.
Gene: Protein-coding gene on chromosome 7 (94,656,325 to 94,669,695, forward strand). Ensembl gene ENSG00000242265.
Subcellular location: Extracellular vesicle membrane; Cytoplasm; Nucleus
Subcellular location (Human Protein Atlas): Cytosol; Nucleoplasm
Gene Ontology:
Molecular function: protein binding; RNA binding; mRNA binding; nucleic acid binding; zinc ion binding
Biological process: negative regulation of transforming growth factor beta receptor signaling pathway; mRNA transport; placenta development; protein homooligomerization; vesicle-mediated intercellular transport
Cellular component: cytoplasm; nucleus; extracellular vesicle
Genetic constraint (gnomAD): Loss-of-function variants: 8 observed, 27.14 expected, observed/expected ratio (o/e) 0.29, 90% interval 0.17 to 0.53. The upper end of that interval is the gene's LOEUF score, 0.53, which puts it in group 2 of 6, group 1 being the genes least tolerant of losing a copy. Missense variants: 459 observed, 539.94 expected, observed/expected ratio (o/e) 0.85, 90% interval 0.79 to 0.92. Synonymous variants: 178 observed, 202.35 expected, observed/expected ratio (o/e) 0.88, 90% interval 0.78 to 1.
Homologues: Orthologues: chimpanzee PEG10 (99% identical), dog PEG10 (93% identical), rabbit PEG10 (46% identical), pig PEG10 (45% identical), mouse Peg10 (34% identical), rat Peg10 (27% identical). Paralogues in human: RTL1 (20% identical), RTL5 (13% identical), RTL3 (11% identical), RTL4 (7% identical), RTL10 (7% identical), RTL6 (6% identical), RTL8A (5% identical), RTL8B (5% identical), LDOC1 (4% identical), RTL8C (4% identical).